NSD1 (nuclear receptor binding SET domain protein 1)
Diseases named in the same sentence as NSD1 in open-access papers (continued):
Sharing a sentence is not in itself a finding about the gene and the disease.
tumor (continued). "Thus, in vivo Nsd1 ablation triggers an immune cold phenotype that may favor tumor development and represent a marker of immune response." (PMID 36230787, 2022). "In addition, the critical downstream effectors of the tumor suppressive activity of NSD1 remain unknown." (PMID 34575025, 2021). "Additionally, the effect of NSD1 on tumor growth and EMT of BC were also explored." (PMID 34905470, 2021). "Moreover, NSD1 also had an impact on tumor growth, EMT, and paclitaxel sensitivity of BC in vivo." (PMID 34905470, 2021). "Crucially, the authors found that mutations in chromatin regulators like NSD1 were enriched in the Immunity-H group and positively correlated with enhanced immune signatures, suggesting that alterations in NSD-family genes may promote anti-tumor immune activity." (PMID 40586874, 2025). "NSD1/2 and LEDGF/HDGF2 were found to facilitate H3K27 methionine substituted-DMG tumor growth in vivo." (PMID 39765675, 2024). "Collectively, our data clearly demonstrate that NSD1 positively regulates H3K36me2 level in HNSCC and functionally supports HNSCC cells proliferation and tumor growth, both in vitro and in vivo." (PMID 37786686, 2023). "The nine clusters that were identified in our analysis included known HNSC subtypes such as the HPV+ and NSD1/H3K36 impaired groups, aided by inclusion of the tumor-specific microbiome, and DNA-methylation status, respectively." (PMID 35912202, 2022). "Furthermore, their presence in primary, but not in the recurrent tumor, suggests that NSD1 mutations may also be influenced by treatment." (PMID 36611369, 2022). "Functional studies are required to assess the link between NSD1-mutant tumors and the ECM components in tumor aggressiveness." (PMID 36230787, 2022). "This study aimed to reveal the effects of NSD1 on cell migration, invasion, EMT and paclitaxel sensitivity of paclitaxel-resistant BC as well as on tumor growth and EMT in vivo." (PMID 34905470, 2021). "In vitro experiments and prospective cohorts will be required to elucidate the exact role of both NSD1 and DNAH5 on LSCC tumor behavior and response to therapy." (PMID 33396315, 2020). "Four SNVs of NOTCH2, PDE4DIP, ATP10B and NSD1 and one frameshift INDEL of BAP1 were validated by Sanger sequencing on tumour RNA." (PMID 28484631, 2017). "Tissue microarrays (TMAs) using with HNSCC tumor tissues derived from 36 HPV-negative patients revealed that both NSD1 and H3K36me2 protein expression were significantly lower in normal epithelium tissues compared to HNSCC tumor tissues of stages II through IV." (PMID 37786686, 2023). "We also investigated the relationship between the levels of expression of NSD1, NSD2, or NSD3 with tumor-infiltrating lymphocytes (TILs) in either the HPV+ or HPV- HNSCC samples and whether expression of NSD1, NSD2, or NSD3 correlated with overall survival." (PMID 33588906, 2021). "Reduced expression of NSD1 was also reported to be part of an epigenetic gene signature able to distinguish non-malignant tumor from tissue of prostate cancer." (PMID 34575025, 2021). "In addition to the 8 representative PKMTs with tumor suppressor activity, PRDM16, MLL2, MLL4, SET domain bifurcated histone lysine methyltransferase 1 (SETDB1), SETD3, NSD1, NSD3, DOT1L, SUV39H1, and SUV39H2 have also been suggested to possess tumor suppressor activity." (PMID 38036730, 2023). "We posited that molecular classification of the HNSC tumor samples using single data modalities, like RNA-seq or methylation array datasets, might fail to capture the full range of inter tumor heterogeneity and effects of known etiological agents, like HPV+ or NSD1/H3K36 impairment." (PMID 35912202, 2022). "Consistently, combined NSD1 and NSD2 inhibition resulted in significant cytotoxicity in AR-positive PCa cells, whereas inactivation of either genes alone had little to no tumor-killing effect in prostatic cell lines." (PMID 39251788, 2024).
genetic disorder (8 papers, 2018 to 2024). "The prevalence of this genetic disorder is 1:10,000−1:50,000, and it is characterized by wide allelic heterogeneity, with more than 100 different known mutations in the nuclear receptor-binding SET domain containing protein 1 (NSD1) gene." (PMID 30332768, 2018).
hematological malignancies (7 papers, 2015 to 2024). "In the past decades, NSD1/2/3 histone methyltransferases have been shown to play an important role in hematologic malignancies and solid tumors." (PMID 37786686, 2023).
neurodevelopmental disorder (5 papers, 2019 to 2025). A behavioral and cognitive disorder with onset during the developmental period that involves impaired or aberrant development of intellectual, motor, or social functions. "NSD1 is a chromatin-modifying factor linked to transcriptional regulation and a neurodevelopmental disorder, as mutations in the NSD1 gene cause Sotos Syndrome41,42." (PMID 41279818, 2025). "Other highly enriched genes for nsDNV—KMT2D (OMIM 147920), KMT2A (OMIM 605130), NSD1 (OMIM 117550), TAB2 (OMIM 614980), and ADNP (OMIM 615873)—have been previously associated with different types of neurodevelopmental disorders with co-occurrence of CHD." (PMID 34324492, 2021).
head and neck tumors (3 papers, 2019 to 2024). "Improved survival associated with NSD1 mutations in HPV-negative HNSCC is consistent with previously published work showing that NSD1 mutations are a favorable prognostic biomarker in head and neck tumors." (PMID 31321084, 2019).
infection (2 papers, 2018 to 2025). The state of being infected such as from the introduction of a foreign agent such as serum, vaccine, antigenic substance or organism. "The NSD-1 protein was specifically expressed in the larval midgut epithelium, the known infection site of BmDV." (PMID 29743532, 2018).
psychiatric diseases (2 papers, 2020). "The next three P/LP variants (one P, two LP) were identified in two genes and at a chromosomal position, each implicated in neurological or psychiatric disorders with or without seizures (NSD1, 10q11.22-q11.23 deletion, and GABRA5)." (PMID 32938993, 2020).
infectious disease (1 paper, 2023). A disorder directly resulting from the presence and activity of a microbial, viral, or parasitic agent in humans. "However, the role of NSD1 in infectious diseases in humans has not been thoroughly studied." (PMID 37176149, 2023).
NSD1 also shares sentences with these, for which no sentence is quoted: glioma (10 papers); glioblastoma (5); Tatton-Brown-Rahman syndrome (4); anemia (3); Malan syndrome (3); multiple myeloma (3); Thrombocytopenia (3); carcinoma in situ (2); colorectal cancer (2); Cornelia de Lange syndrome (2); Cowden syndrome (2); growth disorder (2); Hunter-McAlpine craniosynostosis syndrome (2); intellectual disability syndrome (2); learning disabilities (2); Lipedema (2); myelodysplastic syndrome (2); neurologic disorder (2); 22q11.2 deletion syndrome (1); achondroplasia (1); acute kidney injury (1); allergic asthma (1); amnesia (1); aortic stenosis (1); Ataxia (1); B cell lymphoma (1); Barth syndrome (1); bradyopsia (1); cancer of the peripheral nervous system (1); cancers of the brain (1).
A further 63 diseases each share a sentence with NSD1 in 1 paper.